DTNB (dystrobrevin beta)
Description:
Scaffolding protein that assembles DMD and SNTA1 molecules to the basal membrane of kidney cells and liver sinusoids (By similarity). May function as a repressor of the SYN1 promoter through the binding of repressor element-1 (RE-1), in turn regulates SYN1 expression and may be involved in cell proliferation regulation during the early phase of neural differentiation. May be required for proper maturation and function of a subset of inhibitory synapses (By similarity).
Tractability: Antibody: its Gene Ontology location is reachable by antibodies, with high confidence; UniProt places it where antibodies can reach, with medium confidence. PROTAC: its protein half-life has been measured.
Gene: Protein-coding gene on chromosome 2 (25,377,028 to 25,673,717, reverse strand). Ensembl gene ENSG00000138101.
Subcellular location: Cytoplasm; Postsynaptic density; Cell projection, dendrite; Basal cell membrane; Postsynapse; Nucleus
Subcellular location (Human Protein Atlas): Golgi apparatus
Pathways (Reactome):
Extracellular matrix organization: Formation of the dystrophin-glycoprotein complex (DGC)
Gene Ontology:
Molecular function: protein binding; zinc ion binding
Biological process: neuron differentiation; camera-type eye development; synaptic signaling
Cellular component: cytoplasm; nucleus; basal plasma membrane; dystrophin-associated glycoprotein complex; inhibitory synapse; plasma membrane; postsynapse; postsynaptic density; synapse; dendrite
Genetic constraint (gnomAD): Loss-of-function variants: 62 observed, 81.83 expected, observed/expected ratio (o/e) 0.76, 90% interval 0.62 to 0.94. The upper end of that interval is the gene's LOEUF score, 0.94, which puts it in group 3 of 6, group 1 being the genes least tolerant of losing a copy. Missense variants: 739 observed, 799.53 expected, observed/expected ratio (o/e) 0.92, 90% interval 0.87 to 0.98. Synonymous variants: 275 observed, 280.28 expected, observed/expected ratio (o/e) 0.98, 90% interval 0.89 to 1.08.
Homologues: Orthologues: chimpanzee DTNB (99% identical), macaque DTNB (92% identical). Paralogues in human: DTNA (74% identical), PLEC (22% identical), DST (22% identical), MACF1 (21% identical), SPTBN1 (21% identical), SPTBN2 (20% identical), SYNE1 (20% identical), SPTBN4 (19% identical), SPTB (19% identical), SYNE2 (18% identical), UTRN (18% identical), FLNA (17% identical), and 24 more.
Diseases named in the same sentence as DTNB in open-access papers:
DTNB is named in the same sentence as 8 diseases in open-access papers, as found by Europe PMC text mining. Sharing a sentence is not in itself a finding about the gene and the disease. The quoted sentences say what the papers report.
Alzheimer disease (2 papers, 2022 to 2025). A progressive, neurodegenerative disease characterized by loss of function and death of nerve cells in several areas of the brain leading to loss of cognitive function such as memory and language. "Dysfunctional DTNB expression has been linked to neurodegenerative conditions such as Alzheimer’s disease and schizophrenia." (PMID 40244254, 2025).
bipolar disorder (1 paper, 2015). A disorder of the brain that causes unusual shifts in mood, energy, activity levels and the ability to carry out day-to-day tasks. "We identified three rare deletions in KCNJ6, UNC13C, OTOL1 and 7 rare duplications in CNTNAP2/MIR548F3, CORO7/VASN, DTNB, EMID2, KCNF1, PDPR and SGTA/THOP1 that are present in children with bipolar disorder (and their parents)." (PMID 25887117, 2015).
dementia (1 paper, 2022). Loss of intellectual abilities interfering with an individual's social and occupational functions. "The results suggest that rare variants in IFFO1, DTNB, NLRC3, and SLC22A10 heighten susceptibility to neuronal injury and inflammation, potentially by altering cytoskeleton structure and immune activity disinhibition, resulting in an elevated dementia risk." (PMID 35173266, 2022).
muscular dystrophy (1 paper, 2018). Muscular dystrophy (MD) refers to a group of more than 30 genetic diseases characterized by progressive weakness and degeneration of the skeletal muscles that control movement. "DTNB is a component of the dystrophin-associated protein complex, which acts as a scaffold for signalling proteins, with abnormalities in this complex leading to muscular dystrophy." (PMID 30212457, 2018).
tumour (1 paper, 2019). "They found higher degree of methylation of MGMT, RARβ, RASSF1A, and CDH13 in tumour specimens and of SOCS-1 in peripheral blood with higher levels of IL-6, while others found less degree of methylation of USP2, TMEM49, SMAD3, DTNB, and IL-6 promoter with higher levels of IL-6." (PMID 31205673, 2019).
DTNB also shares sentences with these, for which no sentence is quoted: schizophrenia (2 papers); depression (1); multiple myeloma (1).